XRCC5 (X-ray repair cross complementing 5)
Diseases named in the same sentence as XRCC5 in open-access papers (continued):
Sharing a sentence is not in itself a finding about the gene and the disease.
colon carcinoma (continued). "Additionally, overexpression of XRCC5attenuated the suppression effect of celecoxib (a COX-2 inhibitor) on colon cancer cell proliferation, which implicates that XRCC5 affects colon cancer cell proliferation via regulating COX-2." (PMID 29049411, 2017). "Furthermore, we evaluated the effect of different XRCC5 expressions on colon cancer cell proliferation in vitro and growth of tumor xenografts in mice in vivo." (PMID 29049411, 2017). "p300 interacts with XRCC5 by its HAT acetylating XRCC5 in colon cancers." (PMID 29049411, 2017). "Finally, we evaluated the effect of p300/XRCC5 cooperation on colon cancer cell proliferation." (PMID 29049411, 2017). "Therefore, we hypothesized that XRCC5 could promote colon cancer cell proliferation via increasing COX-2 expression." (PMID 29049411, 2017). "To determine the expression pattern of core NHEJ genes in colon cancer, we performed Oncomine analysis for XRCC6 (Ku70), XRCC5 (Ku80), PRKDC (DNA-PKcs), XRCC4 (XRCC4), LIG4 (DNA ligase 4), NHEJ1 (XLF), and PAXX (PAXX/XLS)." (PMID 33195430, 2020). "This analysis revealed upregulation of XRCC5, PRKDC, and PAXX in colon cancer compared to normal colon tissues, while LIG4 and NHEJ1 (XLF) displayed downregulation." (PMID 33195430, 2020). "In summary, our current study has revealed that XRCC5 acts as a transcription factor binding to the promoter region of COX-2 and up-regulating the activity of COX-2 promoter in colon cancers." (PMID 29049411, 2017). "Cell viability assay indicated that the overexpression of wild-type p300, but not its histone acetyltransferase (HAT) domain deletion mutant, increased XRCC5 acetylation, thereby up-regulated COX-2 expression and promoted the growth of colon cancer cells." (PMID 29049411, 2017). "Collectively, these results demonstrated that p300 interacted with XRCC5 and acetylated the latter to co-regulate COX-2 expression andcell growth of colon cancer cells." (PMID 29049411, 2017). "In the present study, we proved that XRCC5 bound to the promoter region of COX-2 gene and increased transcription of COX-2 to promote proliferation of colon cancer cells." (PMID 29049411, 2017). "XRCC5 also acts as a binding factor by cooperating with P300 to bind to the COX-2 gene promoter, thus increasing COX-2 expression and subsequently promoting colon cancer growth." (PMID 34079797, 2021). "We further investigated whether p300 cooperated with XRCC5 to regulate COX-2 expression and tumor growth in colon cancer." (PMID 29049411, 2017). "Taken together, our results demonstrated that XRCC5 promoted colon cancer growth by cooperating with p300 to regulate COX-2 expression, and suggested that the XRCC5/p300/COX-2 signaling pathway was a potential target in the treatment of colon cancers." (PMID 29049411, 2017). "Western blot also showed that in colon cancer cells, overexpression of p300 increased COX-2 expression and acetylation of XRCC5, HAT inhibitor (C646) of p300 decreased COX-2 expression and acetylation of XRCC5." (PMID 29049411, 2017). "So XRCC5 might be a transcription factor of COX-2 and promote COX-2 expression in colon cancer cells." (PMID 29049411, 2017). "To further evaluate whether a correlation between XRCC5 and COX-2 expression in colon cancer cells existed, we determined their expression in colon cancer cells (RKO, LoVo, DLD-1, and SW480) at protein and RNA levels respectively." (PMID 29049411, 2017). "However, LPS only increased COX-2 expression, but did not affect XRCC5 expression in colon cancer xenografts." (PMID 29049411, 2017). "However, overexpression of p300 and its HAT inhibitor (C646) did not affect total expression of XRCC5 in colon cancer cells." (PMID 29049411, 2017). "Our analysis revealed that BRAF mutant colon cancer did not harbor higher NHEJ1 expression compared to BRAF wild type tumors and three NHEJ pathway genes, XRCC5, PRKDC, and LIG4 are indeed lowly expressed in BRAF mutant tumors." (PMID 33195430, 2020).
lung carcinoma (17 papers, 2008 to 2025). "The variables of XRCC5 (rs1051685, rs6941) were associated with hematologic toxicity in lung cancer patients treated with platinum-based chemotherapy, which means it can predict platinum-based chemotherapy toxicity in lung cancer patients." (PMID 38137354, 2023). "STIR1 rs3740051 and XRCC5 rs1051685 polymorphisms were associated with the prognosis significantly in lung cancer patients treated with platinum-based chemotherapy." (PMID 38137354, 2023). "It was also reported that the transcriptional overexpression of XRCC5 showed a significant correlation with a shorter patient outcome in advanced lung cancer patients." (PMID 38137354, 2023). "Our early study also shows that XRCC5 promotes proliferation of lung cancer cells via increasing COX-2 transcription." (PMID 29049411, 2017). "Our previous study showed that CBP acetylated XRCC5 to regulate its ability to bind to the promoter region of COX-2 gene in lung cancer cells." (PMID 29049411, 2017). "Gene and protein expression of two DNA repair genes, XRCC3 and XRCC5, were lower in B[a]P-treated E6-positive cells than in E6-negative lung cancer cells." (PMID 26918347, 2016). "Thus, XRCC3, XRCC5, DNA adduct levels, and HPV 16 E6 oncoprotein levels were contributors to EGFR gene mutation in lung cancer patients." (PMID 26918347, 2016). "Clinically, XRCC5 and XRCC6 single nucleotide polymorphisms as well as epigenetic silencing of these genes can lead to the development of multiple cancers, such as CRC, breast and lung cancer." (PMID 26755646, 2016). "The XRCC5 rs1051685 SNP has been associated with susceptibility to myeloma, hematologic toxicity in lung cancer patients treated with platinum-based chemotherapy, and the prognosis of non-metastasic lung cancer patients." (PMID 39457514, 2024). "Our previous study has shown that XRCC5 binds to the promoter region of COX-2 gene and promotes transcription of COX-2 in lung cancer cells." (PMID 29049411, 2017). "Our previous study has shown that XRCC5 binds to COX-2 gene promoter and increases COX-2 expression to promote lung cancer cell proliferation." (PMID 29049411, 2017). "After knockdown of HPV16 E6 in HPV-positive lung cancer TL-1 cells, the expression of XRCC3 and XRCC5 genes was increased in response to the B[a]P treatment compared with their parental cells." (PMID 26918347, 2016). "In the HPV-positive lung cancer cells, after knockdown HPV16 E6 expression, the promoter hypermethylation of the XRCC3 and XRCC5 genes was decreased." (PMID 26918347, 2016). "The protein expression of hMLH1, hMSH2, XRCC1, XRCC3, XRCC5, BRCA1, and BRCA2 repair genes in B[a]P-treated HPV-positive and -negative lung cancer cells was analyzed by western blotting." (PMID 26918347, 2016).
hepatocellular carcinoma (14 papers, 2013 to 2025). A malignant tumor that arises from hepatocytes. "High expression of XRCC5 (X-ray Repair Cross Complementing 5) is associated with metastasis through the Wnt signalling pathway and predicts poor prognosis in patients with hepatocellular carcinoma." (PMID 36143471, 2022). "It was also reported that XRCC5 gene polymorphism effect the prognostic of hepatocellular Carcinoma and melanoma, as a risk factor." (PMID 27852033, 2016). "Additionally, high XRCC5 expression is associated with tumour size, microvascular invasion, and lower overall survival time in the clinical samples of patients with hepatocellular carcinoma." (PMID 37679817, 2023). "Inhibition of XRCC5 expression leads to a significant reduction in the migration and invasion abilities of hepatocellular carcinoma cells." (PMID 37679817, 2023). "In hepatocellular carcinoma, there is a positive correlation between XRCC5 expression level and the migration and invasion abilities of hepatocellular carcinoma cells." (PMID 37679817, 2023). "Overexpression of XRCC5 and XRCC6 was significantly associated with the clinical stage and pathological grade of hepatocellular carcinoma." (PMID 37679817, 2023). "Ren and colleagues illuminated that miR-623 functioned as a tumor suppressor in hepatocellular carcinoma through modulating the phosphoinositide 3‐kinase/protein kinase B (PI3K/Akt) pathway via targeting X-ray repair cross complementing 5 (XRCC5)." (PMID 32766708, 2020). "It has been recently reported that a significant increase in XRCC5 expression in hepatocellular carcinoma mice can prevent liver tumors induced by DNA damage." (PMID 27852033, 2016). "Extensive research on hepatocellular carcinoma (HCC) cell lines has demonstrated that elevated DNA-PK levels are closely associated with increased expression of key DNA repair proteins, particularly XRCC6 and XRCC5." (PMID 40256842, 2025). "Through this regulatory function, XRCC5 promotes the progression of hepatocellular carcinoma." (PMID 37679817, 2023). "In addition, we performed RIP analysis which showed XRCC5 as a potential protein related to DNA damage repair in hepatoma cells." (PMID 35903292, 2022). "Moreover, they observed a significant correlation between the expression of XRCC5 and XRCC6 and the infiltration of B cells, CD4+ T cells, CD8+ T cells, macrophages, neutrophils, and dendritic cells in hepatocellular carcinoma." (PMID 37679817, 2023).
melanoma (13 papers, 2010 to 2025). A malignant, usually aggressive tumor composed of atypical, neoplastic melanocytes. "In the case of melanoma, our top ranked gene was XRCC5, which is involved in double-strand break repair of DNA has been shown to be upregulated in metastatic melanoma patients with significantly worse prognosis." (PMID 29017547, 2017). "In contrast, RAS pathway mutant melanoma cells frequently rely on RAS pathway signaling to facilitate DNA repair by driving gene expression of major DNA repair factors such as BRCA2, BRIP1/FANCJ, and XRCC5." (PMID 40560846, 2025). "In a melanoma cell line model, it has been shown that mutant BRAF inhibition may increase DNA damage by downregulation of NHEJ pathway genes, including XRCC6, XRCC5, and PRKDC." (PMID 33195430, 2020).
prostate carcinoma (13 papers, 2011 to 2022). A carcinoma that arises from epithelial cells of the prostate gland. "Fourteen DNA repair genes and 15 hormone-regulated genes contributed to the high trigger score for the 7p14.3 variant, of which DAZAP2, DDX18, SET, and XRCC5 were also significantly deregulated in SPOP mutant as compared to SPOP wild-type human prostate carcinoma cases." (PMID 28663546, 2017).
colorectal cancer (10 papers, 2006 to 2025). A primary or metastatic malignant neoplasm that affects the colon or rectum. "The present retrospective cohort study aimed at investigating whether MLH1,APEX1,MUTYH,OGG1,NUDT1,XRCC5, XPA, and ERCC2 single nucleotide polymorphisms (SNPs) are associated with colorectal cancer (CRC) in Chinese population with Lynch syndrome." (PMID 29664240, 2018). "A previous study had also reported higher mRNA and protein levels of PRKDC in colorectal cancer tissues compared to normal tissues, which also exhibited a positive correlation with expression of XRCC6 and XRCC5." (PMID 33195430, 2020).
gastric cancer (9 papers, 2017 to 2025). A primary or metastatic malignant neoplasm involving the stomach. "Overexpression of XRCC5 was also detected in gastric cancer, in which XRCC5 regulated the overexpression of chloride channel 3 (CLC3)." (PMID 33006365, 2020). "Our findings indicate that overexpression of CLC-3 is regulated by XRCC5 and is a poor prognostic biomarker for gastric cancer." (PMID 30217218, 2018). "In summary, this study has illustrated that overexpression of CLC-3 is regulated by XRCC5 and is a poor prognostic biomarker for gastric cancer." (PMID 30217218, 2018). "Recently, high expression of XRCC5 has been found in breast and gastric cancer." (PMID 33006365, 2020). "XRCC5 knockdown suppressed binding of XRCC5 to the CLC-3 promoter and decreased its promoter activity in gastric cancer." (PMID 34079797, 2021).
lung adenocarcinoma (9 papers, 2012 to 2023). A carcinoma that arises from the lung and is characterized by the presence of malignant glandular epithelial cells. "The other investigation also found that XRCC5 was an independent risk factor affecting the prognosis of lung adenocarcinoma patients." (PMID 38137354, 2023). "XRCC5 was overexpressed in lung adenocarcinoma, it may be a risk factor, and it can also predict a poor prognosis in lung adenocarcinoma patients." (PMID 38137354, 2023). "XRCC5 (also called Ku80 or Ku86) is an essential component of the NHEJ pathway, and it is highly expressed in lung adenocarcinoma and promotes cisplatin resistance." (PMID 36408135, 2022).
bladder cancer (8 papers, 2011 to 2025). "In one such example a VNTR in the promoter of the human X-ray repair cross-complementing 5 (XRCC5) gene is a risk factor for bladder cancer." (PMID 21346820, 2011). "Furthermore, fewer tandem repeats in the promoter of XRCC5 was associated with enhanced levels of the XRCC5 protein in bladder cancer patients." (PMID 33685509, 2021).
glioma (7 papers, 2013 to 2023). A benign or malignant brain and spinal cord tumor that arises from glial cells (astrocytes, oligodendrocytes, ependymal cells). "XRCC5 knockdown significantly enhanced the sensitivity of glioma cells to TMZ, whereas XRCC5 overexpression led to TMZ resistance in cancer cells." (PMID 37679817, 2023). "In addition, it is observed that miRNA-188-5p regulates glioma cell metastasis by suppressing XRCC5 expression." (PMID 37679817, 2023). "XRCC5, a downstream gene of miRNA-188-5p, was reported to be upregulated in glioma samples." (PMID 37679817, 2023). "Compared with the previous studies, we found that XRCC5 gene is not a risk factor, can be used as a negative factor with prognostic effect of glioma." (PMID 27852033, 2016). "CircXRCC5 acts as a sponge for miR-490-3p and regulates the expression of the downstream target gene, XRCC5, thereby activating CLC3 transcription and promoting glioma progression." (PMID 37679817, 2023). "Ku80 and DNA-PKc (also called XRCC5 and XRCC7, respectively) have been found hypermethylated in glioma." (PMID 28931650, 2017). "Here we investigate the role of 10 potential SNPs in XRCC3, BRCA2, RAG1, XRCC5, LIG4, XRCC4 and ATM in the development of gliomas, and further evaluate their gene-gene and gene-environment interactions in the development of glioma." (PMID 23663450, 2013). "We genotyped 10 potentially functional single nucleotide polymorphisms (SNPs) in 7 DNA double-strand break repair pathway genes (XRCC3, BRCA2, RAG1, XRCC5, LIG4, XRCC4 and ATM) in a case–control study including 384 glioma patients and 384 cancer-free controls in a Chinese Han population." (PMID 23663450, 2013).
ovarian carcinoma (7 papers, 2010 to 2025). A malignant neoplasm originating from the surface ovarian epithelium. "Among these, CTNNB1, CDH1, XRCC5 are important ovarian cancer genes." (PMID 25803614, 2015). "In ovarian cancer cells (A4-T), irregular chromosomal segregation also occurred when silencing RAD50 and XRCC5, under conditions of genomic stress." (PMID 37407587, 2023). "Nevertheless, the mRNA levels of XRCC3 and XRCC5 were uncorrelated to PFS and OS in ovarian carcinoma patients." (PMID 34539898, 2021).
Immunodeficiency (6 papers, 2013 to 2021). Failure of the immune system to protect the body adequately from infection, due to the absence or insufficiency of some component process or substance. "Deletion of XRCC5 in mice has resulted in immune deficiency, growth retardation, increased chromosomal instability, and cancer." (PMID 30783131, 2019).
liver cancer (6 papers, 2008 to 2025). An epithelial or non-epithelial malignant neoplasm that arises from the liver. "Recent studies have shown that SNORD88B is highly expressed in liver cancer stem cells (CSCs) and liver cancer samples, where it promotes the binding of XRCC5 to the STK4 promoter, thereby inhibiting STK4 transcription." (PMID 40584410, 2025).
esophageal squamous cell carcinoma (5 papers, 2018 to 2024). Esophageal squamous cell carcinoma (ESCC) is a type of esophageal carcinoma (EC) that can affect any part of the esophagus, but is usually located in the upper or middle third. "However, XRCC5 knockdown inhibits cell proliferation and increases chemoradiotherapy sensitivity in esophageal squamous cell carcinoma lines." (PMID 36408135, 2022).
myeloma (5 papers, 2008 to 2024). "Many efforts have been made to develop the evaluation of the therapeutic effect of myeloma patients based on NHEJ (WHSC1, XRCC5 (KU80), PNKP, POLL), HR (EXO1, BLM, RPA3, RAD51, MRE11A and ATM) genes in MM patients 8-12." (PMID 35414773, 2022).
thyroid cancer (5 papers, 2016 to 2025). "A study of a Chinese ethnic population evaluated the association of SNPs in the 3′-UTR double-strand break repair genes RAD51, RAD51B, BRCA1 (rs12516, rs8176318), BRCA2 (rs15869), XRCC4, and XRCC5 with the risk of thyroid cancer in 206 patients with PTC." (PMID 40361383, 2025). "The number of reports on the association between XRCC5 polymorphisms and thyroid cancer in various populations remains insufficient." (PMID 38892180, 2024). "XRCC5/Ku80 gene polymorphisms have been investigated in the context of thyroid cancer." (PMID 38892180, 2024). "NHEJ- (XRCC6, XRCC5, PRKDC) and HR‐ (SSBP1, SEM1, RPA2, RPA3)-related genes were found to be expressed in both normal follicular and thyroid cancer cells." (PMID 38380364, 2024). "NHEJ- (XRCC6, XRCC5, PRKDC) and HR- (SSBP1, SEM1, RPA2, RPA3) related genes are expressed by both normal follicular and thyroid cancer cells." (PMID 38380364, 2024). "Interestingly, XRCC5 (Ku80), XRCC6 (Ku70) and RAD50 are members of the non-homologous end joining (NHEJ) DNA repair machinery and are recurrently mutated genes in thyroid cancer according to the Catalogue of Somatic Mutations in Cancer (COSMIC) database." (PMID 26870890, 2016).
non-small cell lung carcinoma (4 papers, 2015 to 2022). A group of at least three distinct histological types of lung cancer, including non-small cell squamous cell carcinoma, adenocarcinoma, and large cell carcinoma.
Hyperglycemia (3 papers, 2024 to 2025). An increased concentration of glucose in the blood. "Hyperglycemia enhances DNA damage in MSCs; hence, we assessed the expression of DNA repair markers XRCC5, TERF1, CDKN1A, and SIRT1 in ASCs in a diabetic milieu." (PMID 38880916, 2024).
leukemia (3 papers, 2011 to 2021). A malignant (clonal) hematologic disorder, involving hematopoietic stem cells and characterized by the presence of primitive or atypical myeloid or lymphoid cells in the bone marrow and the blood. "Likewise, some polymorphisms in both XRCC5 and XRCC6 genes increased the risk of leukemia in a Chinese population." (PMID 34732266, 2021).
lupus (3 papers, 2013 to 2019). "In 2D electrophoresis, the visible DNA-bound protein complex in EMSA was excised from a native PAGE gel and sequenced directly, which identified lupus autoantigen Ku70/80 (XRCC5/6), nucleolin (NCL) and HSP90AA1/AB1 as the major constituents of the DNA–protein band." (PMID 23441136, 2013).